GSDME (gasdermin E)
Diseases named in the same sentence as GSDME in open-access papers (continued):
Sharing a sentence is not in itself a finding about the gene and the disease.
deafness (48 papers, 2012 to 2025). An inherited or acquired condition characterized by the complete loss of the ability to hear from one or both ears. "In conclusion, we have successfully identified a novel pathogenic insertion variant of GSDME in a Chinese pedigree that causes deafness, shedding light on the genetic basis of hearing loss within this specific family." (PMID 37864300, 2024). "Nonsyndromic hearing loss (NSHL) is a genetically diverse, highly heterogeneous condition characterised by deafness, and Gasdermin E (GSDME) variants have been identified as directly inducing autosomal dominant NSHL." (PMID 37864300, 2024). "To further elucidate the molecular mechanism underlying the deafness caused by mutations in GSDME, we transfected GSDME mutants into HEI-OC1 cells." (PMID 39066985, 2024). "This study offers novel insights into the mechanisms and treatment of deafness caused by the cytotoxicity of GSDME mutants." (PMID 39066985, 2024). "GSDME was first identified in 1998 and initially named as deafness autosomal dominant 5 (DFNA5)—a gene associated with hereditary hearing loss." (PMID 39526199, 2024). "This fully confirms that the GSDME deafness gene mutation is a gain-of-function mutation, related to the truncation of the GSDME protein caused by the intron 7 mutation leading to exon 8 skipping at the mRNA level." (PMID 36755014, 2023). "Mutations in GSDME (DFNA5), first identified as a deafness gene in 1998, cause a specific type of non-syndromic, autosomal dominant, progressive sensorineural hearing loss." (PMID 36755014, 2023). "In this study, a novel splice site variant c.1183 + 1 G > C in intron 8 of the GSDME gene was identified by deafness gene NGS panel analysis in this family." (PMID 35864542, 2022). "GSDME was originally named deafness, autosomal dominant 5 (DFNA5) because the gene encoding GSDME was found to be closely related to an autosomal dominant form of hearing impairment." (PMID 36703987, 2022). "GSDME, which is also known as deafness, autosomal dominant 5 (DFNA5), was first associated with sensorineural hearing loss in humans." (PMID 35279675, 2022). "GSDME, also known as DFNA5, was initially being identified as a gene associated with deafness, mutations of DFNA5 lead to hearing impairment, and mutations in several different DFNA5 leads to a jump exon eight at the transcriptional level." (PMID 35647057, 2022). "Notably, a gain-of-function mutation in GSDME, known as deafness autosomal dominant 5, is associated with nonsyndromic hearing impairment." (PMID 41208882, 2025). "The deafness caused by GSDME mutations is post-lingual and progressive, suggesting that other factors may induce its pathogenicity, and the age of onset ranges from 10 to 50 years, which may differ from the time point of exposure to the incentives." (PMID 39066985, 2024). "Our findings expand the spectrum of known variants associated with GSDME‐related deafness and may further support both the underlying gain‐of‐function mechanism and functional associations of GSDME hearing loss variants." (PMID 37864300, 2024). "Consequently, the key role of the truncated protein produced by the GSDME exon 8 mutation in the pathogenesis of deafness is evident." (PMID 36755014, 2023). "Most deafness-causing mutations in GSDME lead to the deletion of GSDME C-terminal transcription and could induce spontaneous pyroptosis." (PMID 35279675, 2022). "In combination with its association with deafness, it was found that the expression level of GSDME in tumor cells was significantly lower than that in normal cells, and enhanced GSDME expression had an inhibitory effect on the proliferation of hepatocellular carcinoma cells." (PMID 36350814, 2022). "It suggested that only the variants of GSDME causing exon 8 skipping could give rise to the deafness phenotype." (PMID 35864542, 2022).
deafness (continued). "Indeed, transient expression of deafness-associated GSDME mutant in 293T cells induced pyroptosis, caspase-3 activation, and Cyt c release from the mitochondria." (PMID 30976076, 2019). "GSDME, also known as deafness, autosomal dominant 5 (DFNA5), is localized on chromosome 7 in humans and chromosome 6 in mice, exhibiting ubiquitous expression across various normal tissues, notably including the gastrointestinal tract and kidney." (PMID 40236694, 2025). "GSDME has emerged from relative obscurity (known first as a deafness gene) to become recognized as a significant mediator of inflammatory cell death in cardiovascular disease." (PMID 41550939, 2025). "The GSDM family consists of GSDMA, GSDMB, GSDMC, GSDMD, GSDME (or deafness, autosomal dominant 5, DFNA5), and DFNB59 (or pejvakin)." (PMID 38711020, 2024). "Autosomal dominant deafness-5 (DFNA5) is a subtype of ADNSHL caused by heterozygous variants in the gasdermin E (GSDME, also known as DFNA5) gene." (PMID 35864542, 2022). "GSDME belongs to the gasdermin (GSDM) family and was originally identified as DFNA5 (deafness, autosomal dominant 5)." (PMID 36091790, 2022). "GSDME, also called deafness autosomal dominant 5 (DFNA5), genetic mutations in GSDME induce nonsyndromic hearing loss in humans." (PMID 36189207, 2022). "GSDME, also known as DFNA5 (deafness, autosomal dominant 5), was initially discovered to play a role in hearing impairment." (PMID 35677444, 2022). "GSDME is the first gene known to be involved in monogenic apoptotic deafness, and it is also a tumor suppressor gene with a critical role in major types of tumors." (PMID 36350814, 2022). "Six types of GSDMs paralogous genes, namely GSDMA, GSDMB, GSDMC, GSDMD, and GSDME [also termed deafness, autosomal dominant 53 (DFNA5)], and pejvakin [PJVK; also termed deafness, autosomal recessive 59 9DFNB59)], have been found in humans." (PMID 36003332, 2022). "So far, there are six categories of human gasdermins classified based on the difference in the conserved domain: gasdermin A (GSDMA), gasdermin B (GSDMB), gasdermin C (GSDMC), GSDMD, GSDME/DFNA5 (deafness, autosomal dominant 5)), and DFNB59/Pejvakin)." (PMID 36119049, 2022). "GSDME, also known as deafness autosomal dominant 5 (DFNA5), one of the genes from our gene signature, was first identified for its involvement in inherited hearing impairment." (PMID 34925465, 2021). "The gasdermin family consists of six members: GSDMA, GSDMB, GSDMC, GSDMD, GSDME (also called DFNA5 (deafness, autosomal dominant 5)), and DFNB59 (also known as pejvakin)." (PMID 34522213, 2021). "Gasdermin E (GSDME), also known as deafness autosomal dominant 5 (DFNA5), was identified as a gene involved in an autosomal dominant form of inherited hearing impairment in 1998." (PMID 34433433, 2021). "GSDME, located at chromosome 7p15, was originally identified as DFNA5 (deafness, autosomal dominant 5) since it is found mutated in familial ageing‐related hearing loss." (PMID 33033617, 2020). "Gasdermin E (GSDME), also known as deafness autosomal dominant 5 (DFNA5), was discovered in our lab as a gene responsible for a specific form of nonsyndromic, autosomal dominant hearing loss." (PMID 31434357, 2019). "Previous studies have shown that certain chemotherapy drugs, like 5-FU, induce pyroptosis mediated by cleaved gasderminE (GSDME, also called deafness autosomal dominant 5, DFNA5), and the mechanism of cell death can shift from apoptosis to pyroptosis depending on the GSDME level 20-22." (PMID 39816682, 2025). "It was soon discovered that caspase-3 cleaves GSDME (also known as DFNA5 (deafness, autosomal dominant 5)) and this results in GSDME N-terminal pore formation and pyroptosis, expanding the mechanism by which pyroptosis can be induced beyond caspase-1-mediated cell death." (PMID 38391959, 2024). "Previous studies have suggested that GSDME (also known as DFNA5) is related to deafness." (PMID 35123387, 2022).
deafness (continued). "The mutant GSDME protein generated by the skipping of exon 8 does not cause deafness due to haploinsufficiency, but rather the mutant protein is endowed with a new function that has toxic effects on the auditory system." (PMID 36350814, 2022). "The connection of deafness to the known pore-forming function of GSDME is difficult to reconcile." (PMID 35292781, 2022). "Mutant GSDME, not the deficiency of GSDME, causes deafness, which is autosomal dominant, progressive, non-syndromic and sensorineural." (PMID 35462927, 2022). "In line with gain-of-function of the deafness mutation, GSDME knockout mice show no hearing impairment." (PMID 36189207, 2022). "Gasdermin E (GSDME), of which mutant form was long considered to relate to hereditary hearing impairment, was named human deafness autosomal dominant 5 (DFNA5) on gene level, and GSDME expression is significantly lower in ER-positive breast carcinomas than in ER-negative breast carcinomas." (PMID 34490348, 2021). "The data presented in this study extended the pathogenic variants spectrum of the GSDME gene, provided an important molecular interpretation and diagnosis for these patients with ADNSHL, and promoted the development of genetic counseling for inherited deafness." (PMID 35864542, 2022). "Gasdermin E (GSDME), originally identified as deafness, autosomal dominant 5 (DFNA5), is cleaved specifically by caspase-3 in the linker, generating a GSDME-N fragment that penetrates the membrane, thereby inducing pyroptosis." (PMID 39011036, 2024). "Gasdermin E (GSDME), originally named deafness autosomal dominant 5 (DFNA5), leads to deafness characterized by an autosomal dominant inheritance and gradual loss of hearing, as a result of outer hair cells apoptosis." (PMID 37169767, 2023). "GSDME was first identified as a deaf gene in 1988, also known as DFNA5 (deafness autosomal dominant 5)." (PMID 34381721, 2021). "The Gasdermin E (GSDME), originally known as deafness, autosomal dominant 5 (DFNA5), was discovered on chromosome 7p15.3 with a peculiar form of autosomal dominant, progressive, sensorineural, and non-syndromic deafness." (PMID 34381728, 2021). "A recent study indicated that gasdermin-E (GSDME), which was originally identified as DFNA5 (deafness gene, autosomal dominant 5), could transform caspase-3-mediated apoptosis induced by chemotherapy drugs, etc., into pyroptosis, an inflammatory form of programmed cell death." (PMID 33187328, 2020).
gastric cancer (48 papers, 2012 to 2025). A primary or metastatic malignant neoplasm involving the stomach. "The pyroptosis effector protein GSDME is associated with several types of cancer, ncluding colon, breast, and gastric cancer, exhibiting differential expression and methylation patterns between tumor and normal tissues." (PMID 37679782, 2023). "Indeed, previous studies have reported GSDME promoter methylation in up to 50% of gastric cancers, with a subset showing a significant association with EBV infection." (PMID 41471908, 2025). "Similarly, 5-fluorouracil has been shown to induce caspase-3/GSDME-dependent pyroptosis in gastric cancer cells, shedding light on the mechanisms underlying chemotherapy in gastric cancer." (PMID 39949740, 2025). "Collectively, our results reveal a novel link between EBV-driven DNA methylation and pyroptotic cell death, suggesting that restoration of GSDME expression may enhance therapeutic responses in EBV-associated gastric cancer." (PMID 41471908, 2025). "Inhibition of GSDME expression could accelerate gastric cancer development, confirming that GSDME methylation is crucial to the pathogenesis of gastric cancer and has the potential to serve as a diagnostic marker for this disease." (PMID 38104141, 2023). "Another study confirmed that the combination of BIX-01294 and cisplatin could enhance the anti-cancer chemotherapy effect in gastric cancer cells by causing GSDME-mediated pyroptosis and activating autophagic flux." (PMID 38104141, 2023). "Moreover, GSDME was closely associated with immune checkpoints in most tumors, including gastric cancer." (PMID 35419279, 2022). "Consistently, EBV-infected gastric cancer cell lines exhibited markedly reduced GSDME mRNA and protein expression, indicating that EBV selectively targets GSDME to modulate pyroptotic susceptibility." (PMID 41471908, 2025). "Collectively, these findings demonstrate that EBV infection selectively downregulates GSDME expression in gastric cancer." (PMID 41471908, 2025). "Transcriptomic analysis of The Cancer Genome Atlas (TCGA) data revealed that GSDME expression was selectively suppressed in EBV-positive gastric cancer, while other gasdermin family members were upregulated." (PMID 41471908, 2025). "The introduction of GSDME into gastric cancer tumor cells inhibited their growth, suggesting that GSDME has oncogenic activity." (PMID 40756987, 2025). "Analysis of the TCGA dataset revealed that among gasdermin family members, GSDME is uniquely downregulated in EBV-positive gastric cancer." (PMID 41471908, 2025). "Recent studies have shown that GSDME-expressing gastric cancer cells undergo pyroptosis when treated with chemotherapeutic agents such as 5-FU." (PMID 40756987, 2025). "Conversely, GSDME knockdown negated the gastric cancer growth inhibitory effect induced by ALKBH4 downregulation and 5-FU treatment." (PMID 38902235, 2024). "Mechanistically, ALKBH4 inhibits GSDME activation at the transcriptional level by inhibiting H3K4me3 histone modification in the GSDME promoter region, thereby reducing the sensitivity of gastric cancer cells to 5-FU treatment." (PMID 38902235, 2024). "In gastric cancer, tanshinone I suppresses cisplatin-resistant cell growth by activating the NF-κB/caspase-3/8/GSDME signaling pathway and stimulating pyroptosis." (PMID 39584140, 2024). "Restoring GSDME expression in gastric cancer cells was shown to enhance their sensitivity to chemotherapy and promote tumor shrinkage." (PMID 38571505, 2024). "The mechanism of action of ALKBH4 in gastric cancer involves reducing the level of H3K4me3 modification in the promoter region of GSDME by acting as a demethylase, leading to the inhibition of GSDME transcriptional activation." (PMID 38902235, 2024). "Other studies have indicated that 5-fluorouracil can trigger caspase-3 activation and GSDME cleavage in gastric cancer cells, thereby converting caspase-3-dependent apoptosis into pyroptosis." (PMID 38756442, 2024).
gastric cancer (continued). "In summary, our results confirm that ALKBH4 attenuates the sensitivity of gastric cancer cells to 5-FU treatment by inhibiting GSDME transcription." (PMID 38902235, 2024). "To elucidate the underlying mechanism of how ALKBH4 inhibits pyroptosis in gastric cancer cells, we evaluated the impact of ALKBH4 expression on key targets (GSDME, GSDMD, NLRP3, Caspase 1) of the pyroptosis pathway using qPCR and western blot experiments." (PMID 38902235, 2024). "In this study, we found that ALKBH4 inhibited the expression of GSDME in gastric cancer, thereby reducing 5-FU-induced pyroptosis, eventually leading to reduced sensitivity of gastric cancer cells to 5-FU treatment and promoting gastric cancer progression." (PMID 38902235, 2024). "In gastric cancer, studies have shown that a reduction in GSDME expression promotes the progression of gastric cancer." (PMID 36605484, 2023). "Recent studies show that GSDME-expressed gastric cancer cells undergo pyroptosis when treated with chemotherapeutic agents such as 5-FU." (PMID 38104141, 2023). "Another classic antitumor medicine, 5-FU, has been reported to suppress cell viability, promote LDH release, induce membrane bubble formation, and cause pyroptotic cell death via the caspase-3/GSDME pathway in SGC-7901 and MKN-45 gastric cancer cell lines." (PMID 38016064, 2023). "When combined with cis‐platinum, BIX‐01294 (BIX), a specific inhibitor of euchromatic histone‐lysine N‐methyltransferase 2 (EHMT2) histone methyltransferase, lowers cell viability in gastric cancer cells through GSDME‐mediated pyroptotic cell death." (PMID 37752941, 2023). "This indicates that GSDME plays a crucial role in inducing tumor cells pyroptosis by chemotherapeutic agents in gastric cancer treatment." (PMID 38104141, 2023). "The expression level of GSDME was reduced, the growth ability of gastric cancer cells were significantly slowed, and the apoptosis of cells was markedly increased." (PMID 35419279, 2022). "The expression level of GSDME was significantly higher in gastric cancer tissue, HS-746T and MKN74 than in GES-1." (PMID 35419279, 2022). "We divided the samples into 2parts according to the median expression levels of GSDME in gastric cancer and then analyzed the biological processes or signaling pathways involved in high GSDME expression in gastric cancer." (PMID 35419279, 2022). "In gastric cancer cells, 5‐fluorouracil‐induced caspase‐3 activation as well as the cleavage of GSDME; thus, switching chemotherapy drug‐induced caspase‐3‐dependent apoptosis into pyroptosis." (PMID 35567376, 2022). "The significant prognostic significance of GSDME in gastric cancer and the fact that affecting GSDME expression inhibits gastric cancer cell growth suggest that GSDME can be used as a predictive biomarker." (PMID 35419279, 2022). "Currently, Wang and others reported that GSDME promotes gastric cancer progression through caspase-3-dependent pyroptosis." (PMID 36567977, 2022). "In the present study, only GSDME among several pyroptosis genes had prognostic significance in gastric cancer." (PMID 35419279, 2022). "We first observed the expression of GSDME in gastric cancer tissue, gastric cancer cell lines HS-746T and MKN74 and gastric mucosal cells GES-1." (PMID 35419279, 2022). "We then further observed the effect of GSDME on gastric cancer cells by knocking down the expression level of GSDME to observe its effect on gastric cancer cells." (PMID 35419279, 2022). "GSDME, then, has prognostic significance in gastric cancer and can be used as a predictive biomarker." (PMID 35419279, 2022). "Our results show that only GSDME has prognostic significance in gastric cancer, and show that it has an important role in a variety of tumors." (PMID 35419279, 2022). "Regarding pyroptosis-related mediators, GSDMD expression was found to be decreased in gastric cancer, while GSDME expression is low in gastric and skin cancer." (PMID 33467668, 2021).